FGF23 (fibroblast growth factor 23)
Diseases named in the same sentence as FGF23 in open-access papers (continued):
Sharing a sentence is not in itself a finding about the gene and the disease.
cardiovascular disease (continued). "Further, significant elevations in circulating phosphate and FGF‐23 in CKD have been shown to associate with increased morbidity and mortality, particularly from cardiovascular disease." (PMID 33190417, 2020). "In the CKD setting, elevated FGF23 levels are now recognized as a key feature of dysregulated mineral metabolism, and are one of the most robust predictors of cardiovascular disease in this patient population." (PMID 30971270, 2019). "The interrelationship between FGF23 and calcification in the vascular bed opens new research pathways regarding the development and progression of cardiovascular disease, with evident clinical applicability in prognostic, diagnostic, and therapy." (PMID 31542779, 2019). "Growing evidence for a link between Pi and FGF23 excess and increased cardiovascular disease risk in CKD has led to a recent focus on Pi- and FGF23-lowering therapies." (PMID 30393837, 2019). "FGF23 has been shown to contribute to cardiovascular disease by increasing renal sodium uptake leading to volume expansion and hypertension." (PMID 31575945, 2019). "Altogether, FGF23, ESRD, and the cytokines being secreted are independently associated with cardiovascular disease." (PMID 30909513, 2019). "As compared with our patients, patients from the Isakova’s study had more advanced stage of CKD with higher levels of FGF23 and more severe cardiovascular disease." (PMID 30209259, 2018). "Many clinical studies have shown significant relationships between the level of FGF23 and outcomes such as mortality, prevalence of cardiovascular disease, bone fracture, and levels of inflammatory markers." (PMID 29780418, 2018). "An elevated FGF23 level is now considered to be a robust predictor of cardiovascular disease and cardiovascular death in patients with CKD." (PMID 29874852, 2018). "A high concentration of circulating Fibroblast Growth Factor 23 (FGF-23) is also an independent risk factor for kidney disease progression, cardiovascular disease and mortality." (PMID 27770793, 2016). "A rapidly increasing body of evidence supports involvement of the fibroblast growth factor 23 (FGF23)-klotho-vitamin D axis in the pathogenesis of cardiovascular disease in CKD patients." (PMID 26807718, 2016). "Circulating levels of FGF23 are a prognostic factor for cardiovascular disease in patients with CKD15 and in the general population." (PMID 27841294, 2016). "Elevated FGF23 has been linked to several adverse clinical outcomes in patients with CKD, including kidney disease progression, cardiovascular disease and death." (PMID 27495287, 2016). "To date, there are few data available addressing the potential role of FGF23 in kidney and cardiovascular disease in HIV-positive individuals." (PMID 27176000, 2016). "The link between elevated FGF23 levels and cardiovascular disease is now well established, particularly in CKD." (PMID 26491212, 2015). "In the ULSAM study, 27% of cases had a previous diagnosis of cardiovascular disease, glomerular filtration rate was lower, and age and FGF-23 plasma levels were higher than in the HPFS study." (PMID 24748388, 2014). "Studies trying to show a correlation between FGF-23 and development of cardiovascular disease and mortality have reported contradictory results." (PMID 25295189, 2014). "High serum FGF23 also induces cardiovascular disease through mechanisms unrelated to abnormal phosphate homeostasis." (PMID 24119158, 2013). "Despite a continuously growing body of clinical data linking FGF23 to cardiovascular disease, experimental data supporting direct vascular effects of FGF23 is lacking." (PMID 23577141, 2013). "We also measured serum FGF-23 levels as this bone-derived hormone is a mediator of renal phosphate wasting and stimulated by vitamin D and PTH and has also been linked to cardiovascular disease." (PMID 23029197, 2012).
cardiovascular disease (continued). "Since any increase in serum P level seems to link between CKD and cardiovascular disease, clinical interest in FGF-23 seems to be appropriate." (PMID 21234310, 2010). "Children and adolescents with cardiovascular disease exhibited significantly higher serum FGF-23 levels compared to the control group [standardized mean difference [SMD] = 1.28, 95% confidence interval [CI] 0.53-2.03; I 2 = 93.0%], as determined using a random-effects model." (PMID 41676340, 2026). "However, further studies are needed to explore the potential modifying effects of dialysis-related factors on the FGF23-cardiovascular disease relationship." (PMID 39807363, 2025). "Notably, disturbances in FGF23 homeostasis are associated with CKD progression, cardiovascular disease, and mortality." (PMID 40281613, 2025). "Although FGF-23 plasma concentrations are influenced by renal function, our findings suggest that its association with outcome in ATTR cardiomyopathy extends beyond kidney function alone, similar to other cardiovascular diseases." (PMID 41226753, 2025). "Additionally, the study aimed to evaluate the potential of FGF23 as a biomarker for predicting long-term morbidity or mortality attributable to cardiovascular diseases." (PMID 38846254, 2024). "This might suggest that with more advanced cardiovascular disease the interaction between FGF-23 and CKD regarding cardiovascular outcome attenuates." (PMID 38524235, 2024). "At the same time, some studies have found that Klotho, FGFR1, and FGFR3 are expressed in the vascular wall, which suggests that the vascular wall is the target organ of FGF23, and also that FGF23 is involved in the occurrence and development of cardiovascular diseases." (PMID 39096857, 2024). "The existence of an interaction between FGF23 and inflammation has been suggested, each of which influences the expression and activity of the other, leading to a vicious feedback loop with adverse outcomes, including cardiovascular disease and mortality." (PMID 38791495, 2024). "Also, FGF23 is a marker of kidney function or cardiovascular disease with higher FGF23 levels predicting worse outcome." (PMID 37773536, 2024). "Besides its well-known role for bone mineralization, FGF-23 is discussed as a marker for cardiovascular disease." (PMID 36437429, 2023). "Fibroblast growth factor-23 (FGF-23) is a biomarker of cardiovascular disease and may also be an early marker of cardiac injury in obese but otherwise healthy African American adolescents." (PMID 37660205, 2023). "Hepatic FGF23 generated in the setting of a fatty liver may therefore be a mechanism of cardiovascular disease in NAFLD." (PMID 35231062, 2022). "Besides its role in mineral metabolism, FGF23 has been shown to have a role in cardiovascular diseases." (PMID 35160052, 2022). "In the general population, observational studies have also found an association between high levels of FGF23 and increased risk of cardiovascular disease, cardiovascular mortality, and noncardiovascular mortality, independently of the renal function." (PMID 35612845, 2022). "Recently, it was postulated that elevated circulating FGF23 does not increase cardiovascular disease (CVD) risk without CKD." (PMID 34778257, 2021). "In this way, decreasing phosphate levels could improve the prognosis of patients with cardiovascular disease who have high plasma levels of FGF-23." (PMID 33767635, 2021). "However, evidence on the role of FGF23 in patients on dialysis is incomplete, and some of the data, especially those on cardiovascular disease (CVD), are controversial." (PMID 33000285, 2021). "FGF23 has been proposed to have a protective effect on the vasculature in CKD by reducing vascular calcifications but, despite these findings, high circulating levels of FGF23 have been associated with increased cardiovascular disease independent of CKD." (PMID 33067928, 2020).
cardiovascular disease (continued). "Although these data are not entirely consistent, it may at least partly explain the role of FGF23 in cardiovascular disease as observed in epidemiological studies." (PMID 32857288, 2020). "Given its prominent role as a regulator of phosphate homeostasis, FGF23 may contribute to cardiovascular disease through deregulation of phosphate balance, promoting vascular calcification through increased phosphate deposition in the vascular wall." (PMID 32857288, 2020). "Regardless of the population evaluated, high FGF23 levels are associated with adverse clinical effects such as cardiovascular disease and mortality." (PMID 30909513, 2019). "Inflammation, renal and cardiovascular disease are major triggers of the production of fibroblast growth factor 23 (FGF23), a proteohormone mainly produced in the bone and implicated in the regulation of phosphate reabsorption and 1,25(OH)2D3 (active vitamin D) formation in the kidney." (PMID 30921339, 2019). "A recently published study suggests that FGF23 elevation in the absence of CKD is not causative of cardiovascular disease." (PMID 30909513, 2019). "A recent meta-analysis of prospective studies concluded that the relationship between FGF23 and cardiovascular disease risk is unlikely to be causal." (PMID 31372314, 2019). "The strength of the association was independent of other conditions associated with high FGF23 such as cardiovascular disease or renal disease, which were the same between groups." (PMID 31075857, 2019). "Finally, endogenous FGF23 expression and secretion in infiltrating macrophages in the heart induce cardiovascular disease progression through induction of inflammation and fibrosis." (PMID 29892269, 2018). "Higher FGF-23 levels were also found to be associated with elevated risk of AF development in both patients with and without clinical cardiovascular disease." (PMID 30158498, 2018). "FGF23 has emerged as a powerful biomarker of cardiovascular disease and death in patients with CKD." (PMID 29415048, 2018). "There are several mechanisms that suggest a role of FGF23 in cardiovascular disease." (PMID 28977159, 2017). "The hypothesis of whether FGF23 levels are high in patients with GDM, which brings increased risk of cardiovascular disease, was tested in our study." (PMID 28977159, 2017). "A higher FGF23 level has also been associated with an impaired response to intensified renin–angiotensin–aldosterone system (RAAS)-blockade-based therapy, the key therapy in patients with both kidney and cardiovascular disease." (PMID 29137111, 2017). "Excess FGF-23 is a putative biomarker of cardiovascular disease." (PMID 29291028, 2017). "Several hypotheses have been proposed to explain the link between FGF-23 and cardiovascular disease." (PMID 26462160, 2015). "Elevated fibroblast growth factor-23 (FGF23) is an established marker of cardiovascular disease." (PMID 25811862, 2015). "If indeed cFGF23 is toxic to vessels, targets to interfere in the FGF23 secretion and catabolism could be helpful in preventing cardiovascular diseases." (PMID 26079688, 2015). "Taken together, there is evidence from clinical and experimental studies that FGF-23 may not only be a bystander, but a direct or indirect mediator of cardiovascular disease." (PMID 25528363, 2014). "Vitamin D and fibroblast growth factor-23 (FGF-23) are related with cardiovascular disorders." (PMID 24748388, 2014). "However, the initial onset and gradually accelerating perturbation in FGF23-Klotho expression appear intimately connected with development of cardiovascular disease (CVD)." (PMID 23577141, 2013). "Future studies are needed to elucidate the potential biological mechanisms of FGF23 in the pathogenesis of cardiovascular disease and to evaluate whether FGF23 is a modifiable cardiovascular risk factor." (PMID 24015259, 2013). "Our observations provide an additional evidence of the role of FGF23 in cardiovascular disease." (PMID 24015259, 2013).
cardiovascular disease (continued). "Among them, interleukin 6 (IL-6), tumor necrosis factor-α (TNF-α), and fibroblast growth factor 23 (FGF-23) are robust independent predictors of all-cause mortality in stage 5 CKD patients, with IL-6 also serving as a reliable classifier of clinically overt cardiovascular disease." (PMID 41295836, 2025). "Myokines, including fibroblast growth factor-23 (FGF-23), tumour necrosis factor-related apoptosis-inducing ligand receptor 2 (TRAIL-R2), interleukin-7 (IL-7), and monocyte chemoattractant protein-1 (MCP-1), among others, have been implicated in cardiovascular diseases." (PMID 38930112, 2024). "The totality of the evidence suggests that FGF-23 does not have a direct causal role in the development of cardiovascular diseases, and directly targeting FGF-23 is therefore unlikely to represent a clinically meaningful modifiable target to prevent cardiovascular disease." (PMID 36719157, 2023). "Even though high FGF23 levels have been well recognized to be associated with most of the comorbidities of CKD patients, and in particular with cardiovascular disease (CVD), the pathogenic mechanisms by which FGF23 could induce these effects are far from being clear." (PMID 36569120, 2022). "CKD is related to cardiovascular disease through different mechanisms, among which are the production of inflammatory mediators and ROS, the accumulation of uremic toxins, the toxicity of phosphate, and the activation of the fibroblast growth factor 23 pathway (FGF-23)." (PMID 34682915, 2021). "Despite strong evidence on the effect of elevated FGF23 in cardiac complications followed by kidney disorders, two cohort studies on hemodialysis patients together with non-cardiovascular patients did not manifest any causal correlation between FGF23 levels and cardiovascular disease symptoms." (PMID 34095143, 2021). "As kidney function strongly influences the risk of mortality and cardiovascular disease, the greater hazard of mortality in association with elevated FGF23 in nondialyzed CKD patients might in part be explained by decline in kidney function." (PMID 33163716, 2020). "Therefore, CPPs may induce inflammatory responses that both result in organ damage, including cardiovascular disease, and induce FGF23 in bone cells." (PMID 29780418, 2018). "The present findings suggest that FGF23 could be a useful marker of cardiovascular disease in GDM." (PMID 28977159, 2017). "Inflammation might be another mechanism linking FGF23 to cardiovascular disease." (PMID 27579618, 2016). "Taken together, FGF23 has an undeniable capacity to predict long-term outcome; however, it remains unclear whether this is independent of factors linked to cardiovascular disease risk or renal function." (PMID 25902817, 2015). "Consequently, we hypothesize that the FGF-23/vitamin D axis may be unbalanced in patients with T1DM with early stages of cardiovascular disease." (PMID 26462160, 2015). "Very recent evidence suggests that, within the broad spectrum of cardiovascular diseases, FGF-23 might be a much stronger predictor of incident heart failure events rather than of atherosclerotic vascular events, both among CKD patients, and among subjects with a preserved renal function." (PMID 25528363, 2014). "FGF23 could be a better prognosis predictor of cardiovascular disease than any other biomarkers." (PMID 23705925, 2013). "In addition, knowledge of the full complement of renal gene products regulated by FGF23 in the kidney that might mediate progressive renal damage or kidney processes affecting cardiovascular disease is largely unexplored." (PMID 22970174, 2012). "We analysed other biomarkers that, in recent years, have been related to cardiovascular disease, such as suPAR, FABP4, and MM biomarkers (P, PTH, vitamin D, FGF-23, klotho)." (PMID 39940753, 2025). "On the flip side, FGF23 acts as a potent inhibitor of ACE2, potentially inducing heart fibrosis and consequent cardiovascular disorders." (PMID 38846254, 2024).
cardiovascular disease (continued). "Notably, given that elevated serum FGF23 levels are directly associated with cardiovascular morbidity in patients with or without renal disease, monitoring serum FGF23 levels may be helpful in patients with FHH to assess the risk of cardiovascular diseases." (PMID 38530370, 2024). "In summary, FGF23 is considered an excellent early CKD biomarker and an active mediator of cardiovascular disease (CVD), so new interventions to lower its effects are eagerly researched." (PMID 36498673, 2022). "Low concentrations of α-klotho and high concentrations of FGF23 generally predict the degree of kidney dysfunction at early CKD stages, cardiovascular disease, and death in both subjects with CKD and the general population." (PMID 36221075, 2022). "The aim of this study was to evaluate the relationship between Fibroblast Growth Factor-23 (FGF23) serum levels and cardiovascular disease and early graft failure in renal transplant recipients." (PMID 32257685, 2020). "In this review, we summarize the current knowledge of the role of FGF23 on the phosphate homeostasis in health and CKD, as well as their contribution to cardiovascular diseases." (PMID 31698866, 2019). "Conflicting observational data exists between OCN, FGF23 and LCN-2 and markers of cardiovascular disease in humans, which are discussed further within this review." (PMID 31372314, 2019). "Fibroblast growth factor 23 (FGF 23), an endocrine hormone regulating the homeostasis of phosphate and vitamin D, has been shown to play a role in cardiovascular disease." (PMID 31058117, 2019). "Additional mechanistic studies linking iron metabolism, FGF23 and red cell fate are relevant in CKD given the high risks of cardiovascular disease and death in these patients." (PMID 26079688, 2015). "The discovery of Fibroblast Growth Factor 23 (FGF-23) has introduced a new perspective linking vitamin D metabolism and cardiovascular disease." (PMID 26462160, 2015). "Serum levels of FGF-23 have been shown to predict cardiovascular events in patients with CKD, in patients with normal renal function and a prevalent cardiovascular disease and also among individuals from the general population." (PMID 25528363, 2014). "Elevated FGF23 independently predicts cardiovascular issues and can hinder the response to renin-angiotensin-aldosterone system (RAAS) therapy, vital in treating kidney and cardiovascular disease." (PMID 38846254, 2024). "Therefore, FGF23 and klotho are key participants in CKD-MBD, and they are closely related to the occurrence of vascular calcification and cardiovascular disease." (PMID 34367315, 2021). "The synthesis of FGF23 by extra-osseous calcified tissues and its contribution to cardiovascular disease is an intriguing question not adequately studied." (PMID 31542779, 2019). "The present findings suggest that FGF23 could be a useful marker of cardiovascular disease in GDM; however, comprehensive studies covering larger populations are needed to enlighten the relationship between FGF23 and GDM." (PMID 28977159, 2017). "Although the relationship between FGF23, increased mortality and cardiovascular disease is well established in both CKD and non-CKD populations, the underlying pathophysiological mechanisms remain poorly understood." (PMID 25902817, 2015). "We aimed to describe the effect of the calcium phosphate product (Ca*P) on FGF-23 concentrations in children and young adults without confounding cardiovascular disease." (PMID 23413976, 2013). "The relationship between FGF23 and cardiovascular disease in the absence of CKD also merits further investigation." (PMID 22590632, 2012). "Our findings suggest that it could be of value to add FGF-23 to future similar equations for patients with established cardiovascular disease, with or without CKD." (PMID 38524235, 2024). "However, there are no specific reports addressing the role of FGF23 in cardiovascular disease in SLE patients." (PMID 37627287, 2023).